GJB3 (gap junction protein beta 3)
Diseases named in the same sentence as GJB3 in open-access papers (continued):
Sharing a sentence is not in itself a finding about the gene and the disease.
cancer (18 papers, 2020 to 2025). A tumor composed of atypical neoplastic, often pleomorphic cells that invade other tissues. "We conducted a comprehensive evaluation of the GJB3 gene expression signature, including its prognostic value and association with immune cell infiltration and cancer-associated pathways across various cancer types." (PMID 38728250, 2024). "The molecular mechanisms by which loss of GJB3 leads to aneuploidy and cancer initiation and progression remain unsolved." (PMID 38956497, 2024). "Previous KEGG analysis results have indicated a significant association between GJB3 and the metabolic processes in various cancers." (PMID 38728250, 2024). "Upon reviewing the literature, we noted that research on GJB3 in tumours is limited; thus, we delved deeper into the prognostic role of GJB3 across pan‐cancer settings, finding it to act predominantly as a risk factor in most tumours." (PMID 38958523, 2024). "This study further underscores the significance of GJB3 as a potential target for cancer therapy, particularly in strategies involving the PI3K/AKT signaling pathway." (PMID 38728250, 2024). "GJB3, unique to cancer tissue compared to adjacent normal tissue, was enriched in both Specialized Epithelial Cells and Airway Epithelial Cells." (PMID 39092217, 2024). "Given the pronounced association of GJB3 with the prognosis in LUAD, MESO, and PAAD, we strategically chose these specific cancer cell lines for our in vitro studies to comprehensively investigate its underlying biological functions." (PMID 38728250, 2024). "The expression of GJB3 appears to be correlated with the infiltration of multiple immune cells within tumors in certain cancer types such as TGCT, PRAD, and THYM." (PMID 38728250, 2024). "There are therefore promising implications for the use of GJB3 as a biomarker in the detection, staging, and monitoring of cancers." (PMID 38728250, 2024). "The findings of this study suggest that GJB3 is widely distributed throughout most cancer tissues, and it is commonly expressed at high levels compared with that of normal tissues." (PMID 38728250, 2024). "These genes are GAPDH, FSCN1, SLC2A1, FAM83A, PLEK2, and GJB3, some of which have been previously documented in various cancer types." (PMID 38370379, 2024). "As a consequence of the findings of our study, it appears that GJB3 seems to be significantly related to the prognosis of multiple types of cancer; in particular, LUAD, PAAD, and MESO were significantly associated with patient OS, DSS, and PFI." (PMID 38728250, 2024). "The outcomes mirrored those observed in LUAD cell lines, with GJB3 knockdown significantly impeding both proliferation and migration in these cancer types as well, reinforcing the potential universal role of GJB3 in tumor progression across various cancers." (PMID 38728250, 2024). "The results of the study demonstrated that GJB3 is abnormally expressed and typically predicts a poor outcome in various cancers, especially in LUAD, PAAD and MESO." (PMID 38728250, 2024). "This study provides a comprehensive investigation of the GJB3 gene expression signature and its prognostic significance across multiple human cancers." (PMID 38728250, 2024). "The present study has extensively examined the role of GJB3 in pan-cancer from a bioinformatics perspective; however, there are some limitations." (PMID 38728250, 2024). "A drug sensitivity analysis of GJB3 was performed using the Genomics of Drug Sensitivity in Cancer database." (PMID 38728250, 2024). "Animal experiments verified that GJB3 depletion suppressed the hepatic metastasis of PDAC cancer cells." (PMID 36341459, 2022). "GJB3 aggregates forming puncta at the cancer cell-adipocyte interface were observed." (PMID 40835606, 2025). "Increased GJB3 expression was associated with different types of immune cells, including T cells CD4, T cells CD8, neutrophils, macrophages, and dendritic cells (DC) in various cancer types." (PMID 38728250, 2024).
cancer (continued). "But in ESCA, BRCA, and KIRP cancers, the advanced patients expressed significantly less GJB3." (PMID 38728250, 2024). "For example, the gap junction protein GJB3 is being considered as a therapeutic target for a wide range of cancer types, including lung adenocarcinoma where the knockdown of the protein inhibits the PI3K/AKT pathway and leads to a decrease in proliferation, migration, and viability of cancer cells." (PMID 39595165, 2024). "It is clear from these findings that GJB3 plays a significant role in various cancers, as predicted by our hypothesis." (PMID 38728250, 2024). "Moreover, the abundance of GJB3 expression was significantly increased in different cancer cell lines sourced from the CCLE database, and was also an expression trend in various types of cancers, which were similar to that of previous findings." (PMID 38728250, 2024). "In addition, we evaluated the relationship between GJB3 levels and immune cell scores in the various cancers via different algorithms." (PMID 38728250, 2024). "Our findings indicate that, GJB3 may play an important role in various types of cancer, especially in signal transduction-related pathways, as well as in a variety of metabolic processes." (PMID 38728250, 2024). "Additionally, GJB3 plays a role in different cancer pathways, as well as in different immune and molecular subtypes of cancer." (PMID 38728250, 2024). "Although it is clear that abnormal GJB3 expression correlates with immune cell and prognosis in cancers, it remains uncertain whether GJB3 directly affects patient survival through the immune response." (PMID 38728250, 2024). "GJB6 was conserved only in EGFR-mut and KRAS-mut cancers while the latter also conserved GJB3." (PMID 36612014, 2022). "As for the roles of GJB3 in other cancer metastasis need further researches." (PMID 36341459, 2022). "Thus, GJB3 may be considered an effective biomarker for assessing the efficacy of immunotherapy in these specific cancer types." (PMID 38728250, 2024). "These pieces of evidence showed that GJB3 might be a cancer-promoting gene in LUAD." (PMID 39135979, 2024). "Therefore, we hypothesized that GJB3 may exert its influence in multiple cancer types through the modulation of the PI3K/AKT pathway." (PMID 38728250, 2024). "Moreover, several studies have suggested that GJB3 is a tumor suppressor in many cancers." (PMID 39135979, 2024). "Further analysis of the model genes within MOCM across pan‐cancer settings revealed that ANLN, CCNB1, CDKN3, EXO1, GJB3 and RAD51AP1 were predominantly overexpressed in tumour tissues, while GGT6 and CYP4B1 were highly expressed in normal tissues." (PMID 38958523, 2024). "Further experiments showed that knockdown of GJB3 inhibited the PI3K/AKT pathway and resulted in reduced proliferation, migration, and viability of different cancer cells." (PMID 38728250, 2024). "Thus, GJB3 dysregulation may affect the progression of various cancers." (PMID 38728250, 2024). "Thus, GJB3 may represent a new therapeutic target for a wide range of cancers." (PMID 38728250, 2024). "Mechanistic study revealed that GJB3 form channels between PDAC tumor cells and accumulated neutrophil, which transfer cyclic adenosine monophosphate (cAMP) from cancer to neutrophil cells, which supports the survival and polarization." (PMID 36341459, 2022). "Both HCC1143 GJB3Low (TN) and T47D (RP) co-cultures lacked GJB3 puncta at the cancer cell-adipocyte interface." (PMID 40835606, 2025). "Additionally, both Cox analysis and K-M curves indicated a relationship between the level of GJB3 expression and OS, PFI, and DSS in various cancer types." (PMID 38728250, 2024). "Given the strong correlation between GJB3 and prognosis for LUAD, PAAD, MESO, and LIHC based on K-M curves and Cox analyses, a KEGG investigation was conducted to explore the biological role of GJB3 in these four types of cancers." (PMID 38728250, 2024).
cancer (continued). "Although there have been a large number of studies conducted on members of the connexin family to date, connexin 31, also known as Gap Junction Protein Beta 3 (GJB3), has not received much attention, especially from a pan-cancer perspective." (PMID 38728250, 2024). "For example, we highlighted FAM83A, GJB3 and HAVCR1 as illustrative examples to demonstrate the effectiveness of denoising and validate their prognostic value using independent the cancer genome atlas program (TCGA) clinical data." (PMID 38819253, 2024). "Interestingly, GJB3 can form channels between PDAC tumor cells and accumulated neutrophils, transferring cyclic adenosine monophosphate (cAMP) from cancer cells to neutrophils, thus supporting their survival and polarization." (PMID 37664112, 2023). "Abnormalities in connexin expression are typically accompanied by cancer development; however, no systematic studies have examined the role of Gap Junction Protein Beta 3 (GJB3) in the context of tumor progression and immunity, especially when considering a broad range of cancer types." (PMID 38728250, 2024). "Our immunohistochemical study confirmed this finding, demonstrating increased levels of GJB3 expression in LUAD and SKCM cancer tissues compared with non-cancerous tissues." (PMID 38728250, 2024).
tumor (18 papers, 2014 to 2026). "We have previously identified an unsuspected role for GJB3 showing that the deficiency of this connexin protein induces aneuploidy in human and murine cells and accelerates cell transformation as well as tumor formation in xenograft models." (PMID 38956497, 2024). "We found that increased GJB2 expression was linked to SCC histological classification (p = 0.045) and TNM stage (p = 0.022), while GJB3 expression was linked to larger tumor size (p = 0.045) and increased lymph node metastasis (p = 0.012)." (PMID 38562019, 2024). "Further animal studies showed that GJB3 depletion alleviated the liver metastasis by suppressing the amounts and function of tumor associated neutrophil." (PMID 36341459, 2022). "Similarly, the percentage of tumor associated neutrophils in GJB3 high is about three times compared to the GJB3 low expression counterpart." (PMID 36341459, 2022). "Gene knockdown or ectopic expression of GJB3 or ORP3 indicated the suitability of EXTIM to investigate the impact of specific factors on tumor cell invasion." (PMID 42092764, 2026). "GJB2 was over‐expressed in 65.5% (72/110) of tumor tissues and 51.8% (57/110) of normal tissues, while GJB3 was over‐expressed in 61.8% (68/110) and 48.2% (53/110) of the tumor and normal tissues." (PMID 38562019, 2024). "Based on the tumor clinicopathological stage, we evaluated the level of GJB3 expression in early (Stages I and II) and advanced tumors (Stages III and IV)." (PMID 38728250, 2024). "The expression levels of GAPDH, FSCN1, SLC2A1, FAM83A, PLEK2, and GJB3 all presented significant differences between tumor tissues and normal tissues." (PMID 38370379, 2024). "In vitro experiments using colony formation, EdU, CCK8, transwell migration assays, immunohistochemistry and western blot were performed to investigate the function of GJB3 in tumor progression of various cell lines." (PMID 38728250, 2024). "As a first step, we performed expression analyses of the GJB3 gene in 33/31 types of tumor-normal tissue derived from TCGA and GTEx databases, to determine its level of expression." (PMID 38728250, 2024). "The purpose of this study is to explore the role of GJB3 in the prognosis and tumor microenvironment of LUAD patients." (PMID 39135979, 2024). "Among the tumor genes, we note some that have been implicated in mTOR activation (MAP2K6 and IL17RC) or inhibition (GJB3) and were upregulated or downregulated, respectively, in everolimus-adapted (LT) tumors." (PMID 39541354, 2024). "We conducted immunohistochemical staining of NSCLC tissue samples, revealing significant increases in GJB2 and GJB3 levels in tumor tissue samples compared to the control tissues." (PMID 38562019, 2024). "The results showed GJB3 knockdown barely influence the recruitments of tumor cells to neutrophil, but greatly reduced the survival of neutrophil." (PMID 36341459, 2022). "Gap junction proteins promote stromal-epithelial interactions in tumors, have a role in tumor progression and GJB3 and GJB5 regulate survival of some stem cells." (PMID 24533081, 2014). "The prolonged tumor-free survival and time to ethical endpoint observed for mice bearing GJB3-depleted TN-MYCLow xenografts, which in vitro were less sensitive to gap junction inhibition than TN-MYCHigh cell lines, imply an additional tumor-intrinsic role for Cx31 as well." (PMID 40835606, 2025). "Gap junction protein beta 3 (GJB3) has been reported as a tumor suppressor in most tumors." (PMID 39135979, 2024). "Similarly, we found lower Gjb3 protein levels during tumor progression in the N-butyl-N-(4-hydroxybutyl)-nitrosamine (BBN)-induced mouse BC model." (PMID 38956497, 2024).
tumor (continued). "Collectively, these findings suggest that GJB3 may have both tumor suppressive and tumor promoting properties." (PMID 38728250, 2024). "Thus, we systematically explored the potential effects of GJB3 in tumor microenvironment (TME), immunotherapy, and drug sensitivity of LUAD patients utilizing the bioinformatics methods." (PMID 39135979, 2024). "According to our findings, GJB3 participates in the regulation of the immune system, and its expression may be a predictive marker of tumor immunogenicity and therapeutic response." (PMID 38728250, 2024). "Then, we analyzed the relationship between GJB3 expression and tumor characteristics." (PMID 38728250, 2024). "We found high GJB3 expressed PDAC tumor cell could transport their cAMP to the neutrophil in the liver metastasis tumor microenvironments, which promote the survival and polarization." (PMID 36341459, 2022). "In this study, we found that GJB3 expressed tumor cells could transfer cAMP into the neutrophils, which promoting the metabolism reprograming, N1 to N2 switch and survive, which finally promotes the tumor cells immune escape and PDAC liver metastasis progress." (PMID 36341459, 2022). "In addition, GJB3 has been reported as a tumor suppressor in the majority of tumors." (PMID 39135979, 2024). "Next, we postulate whether GJB3 could regulate the immune tumor microenvironment." (PMID 36341459, 2022). "We firstly evaluated whether the GJB3 could directly affects the proliferation of PDAC tumor cell." (PMID 36341459, 2022). "GJB3 protein expression in human and mouse bladder samples was further assessed by immunohistochemistry (IHC) utilizing tissue microarrays (TMA), which included 26 normal bladder tissue samples and 243 human MIBC tumor samples." (PMID 38956497, 2024).
skin disorder (5 papers, 2015 to 2024). Any deviation from the normal structure or function of the skin or subcutaneous tissue that is manifested by a characteristic set of symptoms and signs. "Up to now, at least 20 genes of human connexins are known, but skin disorders are only connected with mutations in GJB2 (Cx26), GJB6 (Cx30), GJB3 (Cx31), GJB4 (Cx30.3), and GJA1 (Cx43)." (PMID 25575739, 2015).
autosomal recessive hereditary diseases (1 paper, 2021). "Similar reports have shown GJB2/GJB6 and GJB2/GJB3 variants in 11% of deaf children, and genetic interaction between GJB2 and GJB3 in three unrelated families with autosomal recessive hereditary diseases." (PMID 34276761, 2021).
GJB3 also shares sentences with these, for which no sentence is quoted: Hearing impairment (10 papers); Clouston syndrome (3); Hyperkeratosis (2); keratitis (2); Lung squamous cell carcinoma (2); Netherton syndrome (2); adenocarcinoma (1); Alport syndrome (1); Alstrom syndrome (1); autosomal dominant disease (1); biotinidase deficiency (1); Bladder tumors (1); cataract (1); cervical squamous cell carcinoma (1); cholangiocarcinoma (1); colon adenocarcinoma (1); dentinogenesis imperfecta (1); distal renal tubular acidosis (1); endocervical adenocarcinoma (1); epilepsy (1); Esophageal carcinoma (1); genodermatosis (1); hypopharyngeal cancer (1); ichthyosis congenita (1); KID syndrome (1); mesothelioma (1); metabolic disease (1); Skin cutaneous melanoma (1); syndromic (1); Treacher-Collins syndrome (1).
A further 2 diseases each share a sentence with GJB3 in 1 paper.